OTUB1 (OTU deubiquitinase, ubiquitin aldehyde binding 1)
Diseases named in the same sentence as OTUB1 in open-access papers (continued):
Sharing a sentence is not in itself a finding about the gene and the disease.
glioma (8 papers, 2021 to 2025). A benign or malignant brain and spinal cord tumor that arises from glial cells (astrocytes, oligodendrocytes, ependymal cells). "Elevated OTUB1 expression has been associated with the high invasiveness, grade, and metastasis in various tumors including breast, lung, glioma, and ovarian." (PMID 34927544, 2021). "Specifically, OTUB1 stimulated glioma cell stemness by stabilizing the SLC7A11 protein to suppress ferroptosis." (PMID 40469292, 2025). "For instance, OTUB1 in glioma, CRC, GC, and HCC; OTUB2 in BC; OTUD2 in NSCLC; TNFAIP3 in BC and ESCC." (PMID 40469292, 2025). "Mechanistic studies revealed that OTUB1 stabilized SLC7A11 protein via directly interacting with SLC7A11 and OTUB1 knockdown triggered ferroptosis of glioma cells." (PMID 34927544, 2021). "Since CSC is a critical promoter for tumorigenesis and drug resistance, we examined the effects of OTUB1 on glioma stemness and found that OTUB1 positively regulates glioma cell stemness." (PMID 34927544, 2021). "In order to explore the specific mechanisms contributing to OTUB1-mediated effects on glioma stemness, it is particularly important to identify new substrates with potential functions of OTUB1." (PMID 34927544, 2021). "The ubiquitin hydrolase OTUB1 has been elucidated to be highly expressed in tumors, however, its roles in glioma progression are still confusing." (PMID 34927544, 2021). "Since the stemness of tumor cells can be characterized by the sphere-formation ability, we determined OTUB1 effects on the sphere-formation ability of glioma cells." (PMID 34927544, 2021). "Currently, we revealed that OTUB1 is overexpressed in glioma tissues through analyzing clinical samples and online datasets." (PMID 34927544, 2021). "This firstly revealed the effects of OTUB1 on glioma stemness and provided a novel mechanism by which SLC7A11 protein, a critical suppressor of ferroptosis, is regulated in glioma cells." (PMID 34927544, 2021). "Here, via analyzing several online datasets, OTUB1 expression was shown to be remarkably increased in glioma tissues compared to that in the adjacent tissues, and predicted a poor overall survival of glioma patients." (PMID 34927544, 2021). "As CSCs positively engage in cancer occurrence and progression, we evaluated OTUB1 roles in glioma cell stemness." (PMID 34927544, 2021). "Taken together, this work identifies a novel OTUB1/SLC7A11 axis contributing to glioma cell stemness." (PMID 34927544, 2021). "As a deubiquitinase, OTUB1 critically engaged in tumorigenesis and development, but its specific mechanisms contributing to glioma progression remain to be completely elucidated." (PMID 34927544, 2021). "Then OTUB1 was knocked down in glioma cells and it was found that OTUB1 knockdown significantly reduced glioma cell stemness by detecting sphere-formation ability, stemness marker expression, and ALDH activity." (PMID 34927544, 2021). "All in all, these results demonstrate that OTUB1 knockdown reduces glioma stemness dependent on SLC7A11 expression." (PMID 34927544, 2021). "We firstly found that OTUB1 is significantly upregulated in glioma tissues and predicts a poor survival of glioma patients." (PMID 34927544, 2021). "OTUB1 promotes the invasion of glioma cells, and inhibits CNS autoimmune." (PMID 38429268, 2024). "As an example, OTUB1, a deubiquitinating enzyme overexpressed in gliomas, regulates SLC7A11, a critical inhibitory molecule in the ferroptosis Xc-system, directly through the ubiquitinase-proteasome degradation system, forming the OTUB1/SLC7A11 axis and thus promoting the stemness of glioma cells." (PMID 36091118, 2022). "Notably, ectopic expression of SLC7A11 attenuated the inhibition of OTUB1 knockdown on the stemenss of glioma cells." (PMID 34927544, 2021). "SLC7A11 was overexpressed in glioma cells with OTUB1 knockdown." (PMID 34927544, 2021). "A new critical role of OTUB1 in glioma cell stemness is proposed." (PMID 34927544, 2021).
glioma (continued). "This study provides a potential target for glioma treatment by targeting the OTUB1/SLC7A11 axis." (PMID 34927544, 2021). "Silencing function indicated that OTUB1 positively regulated glioma stemness." (PMID 34927544, 2021). "This study firstly indicates that OTUB1 promotes the stemness of glioma cells." (PMID 34927544, 2021). "Notably, a previous work has demonstrated that OTUB1 knockdown attenuates the migration ability of glioma cells, this verifies OTUB1-induced promoting effects on glioma cell stemness as CSC contributes to cancer metastasis." (PMID 34927544, 2021). "The mechanisms of OTUB1 in glioma cell stemness are further studied." (PMID 34927544, 2021). "However, OTUB1 effects on glioma cell viability are still unclear." (PMID 34927544, 2021). "Additionally, knockdown of OTUB1 can suppress glioma cell migration ability in vitro." (PMID 34927544, 2021). "Additionally, co-IP analysis indicated that OTUB1 directly interacted with SLC7A11 in glioma cells." (PMID 34927544, 2021). "Thus, this work identifies a novel OTUB1/SLC7A11 axis contributing to glioma cell stemness." (PMID 34927544, 2021). "Then we speculated that OTUB1 can regulate the ferroptotic process through SLC7A11 in glioma cells." (PMID 34927544, 2021). "Finally, we wondered whether SLC7A11 is responsible for OTUB1 knockdown-induced effects on glioma stemness." (PMID 34927544, 2021). "Thus, this work demonstrates that the OTUB1/SLC7A11 axis could be a potential target for glioma progression." (PMID 34927544, 2021). "However, it is confusing whether OTUB1 regulates glioma stemness." (PMID 34927544, 2021). "OTUD7A expression was significantly decreased in AS, GBM, and ODG, as was OTUB1 in all three types of gliomas compared to non-tumor tissues in the Sun dataset." (PMID 37892185, 2023). "Given the known effect of OTUB1 on SLC7A11 and the critical role of SLC7A11 on ferroptosis, we next investigated whether the OTUB1-dependent effects of glioma cell stemness could be explained within such context." (PMID 34927544, 2021).
colon carcinoma (7 papers, 2015 to 2025). "In order to investigate the curcumol mechanism in inhibiting colon cancer angiogenesis through OTUB1 downregulation and TGFBI ubiquitination, we performed immunoprecipitation (IP) and Western blot analyses." (PMID 40430059, 2025). "Curcumol treatment counteracted these effects by suppressing TGFB1 and VEGF expression following OTUB1 overexpression, reducing colon cancer cell proliferation, migration, and invasion and inhibiting HUVEC tubule formation." (PMID 40430059, 2025). "This study elucidates the mechanism by which curcumol inhibits angiogenesis and metastasis in colon cancer via the OTUB1/TGFB1 pathway." (PMID 40430059, 2025). "A relatively new oncogene, conflicting roles of OTUB1 have been described in colon cancer and lung tumor cell lines." (PMID 27167337, 2016). "It has been shown that OTUB1 and OTUB2 can regulate DNA damage response and OTUB1 has been found elevated in colon carcinomas." (PMID 25623341, 2015). "Mechanistic studies revealed that curcumol downregulates OTUB1, TGFB1, and VEGF expression in both colon cancer and vascular endothelial cells." (PMID 40430059, 2025). "Our study confirmed that OTUB1 overexpression upregulates TGFB1 and VEGF expression, enhancing the proliferative, migratory, and invasive capacities of human colon cancer cells (HT-29 and Caco-2), as well as the tubule formation ability of HUVECs." (PMID 40430059, 2025).
viral infection (7 papers, 2011 to 2024). "In contrast, IL-15 induces the partial redistribution of OTUB1 to the plasma membrane while virus infection causes OTUB1 to be mainly distributed to mitochondria." (PMID 38264570, 2023). "The deubiquitylating enzyme OTUB1 (otubain-1), for example, translocates to the mitochondrion during viral infection to promote the K63 deubiquitylation of TRAF3 and TRAF6, whereas it simultaneously acts as an inhibitor of the proteasomal elimination of RIG-I." (PMID 37940187, 2024). "The deubiquitinases OTUB1/2, UCHL1, MYSM1 and DUBA inhibit K63-linked ubiquitination of TRAF3 or TRAF6 and negatively regulate IFNs production during viral infection." (PMID 29734366, 2018). "After viral infection, HSCARG interacted with tumor necrosis receptor-associated factor 3 (TRAF3) and inhibited its ubiquitination by promoting the recruitment of OTUB1 to TRAF3." (PMID 24763515, 2014). "Similarly, it has been reported that some deubiquitinases including OTUB1/2, UCHL1, MYSM1 and DUBA can remove K63-linked ubiquitination of either TRAF3 or TRAF6, thus inhibiting IFNs production during viral infection." (PMID 29734366, 2018). "Furthermore, the deubiquitinating enzyme OTUB1 was detected with higher abundance in infected cells, indicating a role of this protein in viral infection." (PMID 21933386, 2011). "So far, several deubiquitinases such as DUBA, OTUB1/2, UCHL1, and OTUD7B have been reported to cleave TRAF3 ubiquitin chains in response to viral infection." (PMID 24763515, 2014). "We first screened the reported deubiquitinases for TRAF3 and found that HSCARG interacted with OTUB1 more potently than OTUB2, UCHL1, OTUD7B, and USP25, and this interaction was enhanced by viral infection." (PMID 24763515, 2014).
pancreatic cancer (6 papers, 2016 to 2025). "Accordingly, overexpression and knockdown of OTUB1 phenocopied those of NDUFS2 in pancreatic cancer cells, respectively." (PMID 38653740, 2024). "To further substantiate our conclusions, we checked the effect of OTUB1 on endogenous ubiquitination of NDUFS2 in pancreatic cancer cells." (PMID 38653740, 2024). "To verify the role of OTUB1 in pancreatic cancer, we extracted PAAD (Pancreatic adenocarcinoma) data from the TCGA database while normal tissue data were retrieved from the GTEx database." (PMID 35494004, 2022). "In vitro, overexpressed TFAP2A enhanced pancreatic cancer cell proliferation, suppressed their apoptosis, and promoted the expressions of downstream OTUB1." (PMID 35494004, 2022). "In addition, we confirmed that the levels of NDUFS2 and OTUB1 were positively correlated through Co-IP, both of which were abundantly expressed in pancreatic cancer." (PMID 38653740, 2024). "A recent report showed that OTUB1 could accelerate metastasis of pancreatic cancer by inhibiting FOXM1 degradation." (PMID 38653740, 2024). "Moreover, the growth of OTUB1-overexpressed pancreatic cancer xenograft tumor was promoted in vivo, while the OTUB1-silenced pancreatic cancer xenograft tumor was inhibited in vivo." (PMID 38653740, 2024). "A recent report showed that OTUB1 may accelerate metastasis of pancreatic cancer by inhibiting FOXM1 degradation." (PMID 38653740, 2024). "Analysis of the TCGA database confirmed that OTUB1 expression was significantly elevated in pancreatic cancer tissues than in normal tissues, and that patients with high OTUB1 expressions in pancreatic cancer have significantly lower survival rates than those with low expressions." (PMID 35494004, 2022). "The recent discovery describing how OTUB1 control RAS activity may lead to the development of OTUB1 inhibitors targeting RAS mutation based cancers such as pancreatic cancer, colon and melanoma." (PMID 27516771, 2016). "However, the functions of OTUB1 in pancreatic cancer cells is rarely reported." (PMID 38653740, 2024). "In summary, solasonine inhibits the TFAP2A/OTUB1/SLC7A11 axis to stimulate ferroptosis and prevent the spread of pancreatic cancer cells." (PMID 40070365, 2025). "In conclusion, we revealed that OTUB1 increased the stability of NDUFS2 in PAAD by deubiquitylation and this axis plays a pivotal role in pancreatic cancer tumorigenesis and development." (PMID 38653740, 2024). "Further experiments indicated that overexpression of OTUB1 in pancreatic cancer cells increased the expression of NDUFS2, and knockdown of OTUB1 decreased the expression of NDUFS2 in vitro." (PMID 38653740, 2024). "Then, we filtered all the upregulated and downregulated genes in pancreatic cancer in the online TCGA database, and identified that OTUB1 and NDUFS2 were both upregulated in pancreatic cancer among all the upregulated genes, deciphered by the volcano map." (PMID 38653740, 2024). "Confocal assay showed that OTUB1 and NDUFS2 were co-localized and upregulated in pancreatic cancer tissues compared to the adjacent normal tissues." (PMID 38653740, 2024). "The result showed that OTUB1, as well as NDUFS2, were abundantly expressed in pancreatic cancers in contrast to the adjacent tissues." (PMID 38653740, 2024). "Statistical analysis indicated that the expression of OTUB1 and NDUFS2 in pancreatic cancers was significantly higher than those in normal pancreatic tissues at transcriptional level." (PMID 38653740, 2024). "Collectively, those data suggested that OTUB1 behaved much similarly with NDUFS2 in regulating mitochondrial membrane dynamics and ATP production in pancreatic cancer cells." (PMID 38653740, 2024). "In summary, solasonine inhibits the TFAP2A/OTUB1 SLC7A11 axis to activate ferroptosis and suppress pancreatic cancer cell progression." (PMID 35494004, 2022).
pancreatic cancer (continued). "In conclusion, solasonine is involved in ferroptosis by suppressing TFAP2A-mediated transcriptional upregulation of OTUB1, thereby activating ubiquitinated degradation of SLC7A11 and promoting pancreatic cancer cell ferroptosis." (PMID 35494004, 2022). "Compared to normal tissues, mRNA levels of OTUB1, SLC7A11 and GPX4 were significantly upregulated in pancreatic cancer tissues." (PMID 35494004, 2022). "Considering the importance of OTUB1 and NDUFS2 in mitochondrial metabolism and tumorigenesis, we hypothesized that they may be involved in mitochondrial functions and tumorigenesis of pancreatic cancer." (PMID 38653740, 2024). "The predictive powers of OTUB1, SLC7A11 and GPX4 in pancreatic cancer were highly accurate." (PMID 35494004, 2022). "The primary aim of this study was to investigate whether OTUB1 or NDUFS2 or both of them can be used as new prognostic biomarkers and/or therapeutic targets for pancreatic cancer and shed new lights into exploring therapeutic methods for pancreatic cancer." (PMID 38653740, 2024). "Taking together, our present study revealed that OTUB1 played a crucial role in the development of pancreatic cancer, and NDUFS2, identified as a substrate of OTUB1, might be responsible for the observed phenotypes in the absence of OTUB1 in pancreatic cancer." (PMID 38653740, 2024).
Autoimmunity (5 papers, 2019 to 2023). The occurrence of an immune reaction against the organism's own cells or tissues. "The deletion of OTUB1 in B cell results in B-cell hyperplasia, increased antibody production, increased IL-6 production, and lupus-like autoimmunity." (PMID 38264570, 2023). "There is evidence that OTUB1 represses anti-tumor immunity, innate immunity, and autoimmunity." (PMID 38264570, 2023). "However, the GRAIL/OTUB1 ratio was higher in unstimulated Tregs from B6 mice with respect to NOD mice, showing again that highly and mildly susceptible mice to develop autoimmunity may share some Tregs features." (PMID 31824482, 2019).
liver cancer (5 papers, 2019 to 2024). An epithelial or non-epithelial malignant neoplasm that arises from the liver. "In human liver cancer and other tumor tissues, OTUB1 has been shown to have a high expression and is associated with a poor prognosis in patients." (PMID 35875077, 2022). "Another study also suggested that OTUB1 mediates Forkhead Box M1 (FOXM1) in liver cancer cells." (PMID 34773364, 2021).
osteosarcoma (5 papers, 2018 to 2024). A usually aggressive malignant bone-forming mesenchymal neoplasm, predominantly affecting adolescents and young adults. "MiR‐542‐3p inhibits invasion and migration of esophageal cancer by repressing OTUB1, suppresses the proliferation of osteosarcoma via targeting Smad2, inhibits progression of oral squamous cell carcinoma by impeding ILK/TGF-β1/Smad2/3." (PMID 35427373, 2022).
lung adenocarcinoma (4 papers, 2016 to 2021). A carcinoma that arises from the lung and is characterized by the presence of malignant glandular epithelial cells. "Consistently with these observations, we found that a moderate up‐regulation of OTUB1 is significantly associated with poorer overall survival in TCGA lung adenocarcinoma patients with wt KRAS compared to low‐expressing OTUB1." (PMID 26881969, 2016). "Furthermore, higher levels of OTUB1 expression are observed specifically in lung adenocarcinomas harboring wt KRAS compared to mutated RAS tumors." (PMID 26881969, 2016). "We found that OTUB1 up‐regulation contributes specifically to the development of wt KRAS lung adenocarcinomas by inhibiting reversible ubiquitination of RAS proteins." (PMID 26881969, 2016). "We also observed a higher proportion of wt KRAS lung adenocarcinomas with medium/high levels of OTUB1 expression compared to mutant KRAS tumors." (PMID 26881969, 2016). "Consistent with our TCGA data analysis, OTUB1 positivity was already observed in early stages of lung adenocarcinomas with strong immunoreactivity found in stages T2/T3." (PMID 26881969, 2016). "Compellingly, a moderate up‐regulation of OTUB1 decreases the overall survival of lung adenocarcinoma patients with wt KRAS, suggesting that only medium levels of OTUB1 confers advantage to cancer cells and/or could affect their chemotherapeutic resistance." (PMID 26881969, 2016). "To examine whether OTUB1 is essential for growth, we suppressed OTUB1 expression in lung adenocarcinoma cell lines using OTUB1 shRNAs." (PMID 26881969, 2016). "Although the effects of COPS5 knock-down in SNAIL expression was most predominant amongst the candidates in lung adenocarcinomas, the other four DUBs (JOSD1, OTUB1, OTUD7A, and OTUD7B) could potentially regulate SNAIL expression in other cancer such as cervical cancers." (PMID 29755680, 2018). "Furthermore, either 11q13.1 gain or moderate OTUB1 overexpression is observed at early stages in lung adenocarcinomas with no increase in frequency in higher tumor stages." (PMID 26881969, 2016).
non-small cell lung carcinoma (4 papers, 2020 to 2025). A group of at least three distinct histological types of lung cancer, including non-small cell squamous cell carcinoma, adenocarcinoma, and large cell carcinoma. "Other researchers have proved that SP1 regulates the progression of non-small-cell lung cancer by recruiting OTUB1." (PMID 33537306, 2020). "Moreover, METTL3 increased the expression of circIGF2BP3 through m6A modification, and further enhanced the expression of PD-L1 through the miR-328-3p/miR-3173-5p/PKP3/OTUB1 pathway, ultimately leading to immune escape in non-small cell lung cancer." (PMID 38632251, 2024). "LncRNA LINC01234-induced by SP1 as a ceRNA promotes non-small cell lung cancer by modulating OTUB1." (PMID 31737900, 2020).
diabetic cardiomyopathy (3 papers, 2021 to 2025). Diabetic cardiomyopathy is a disorder of the heart muscle in people with diabetes. "In diabetic cardiomyopathy, OTUB1 interacts with YB-1 to stabilize the YB-1 protein, thereby exerting a protective effect." (PMID 39500879, 2024).
head and neck squamous cell carcinoma (3 papers, 2023 to 2025). A squamous cell carcinoma that arises from any of the following anatomic sites: lip and oral cavity, nasal cavity, paranasal sinuses, pharynx, larynx, and salivary glands. "This study identified OTUB1 as a critical deubiquitinating enzyme (DUB) strongly associated with unfavorable prognoses in head and neck squamous cell carcinoma (HNSCC) patients." (PMID 37986681, 2023).
nasopharyngeal carcinoma (3 papers, 2024 to 2025). A carcinoma arising from the nasopharyngeal epithelium. "In nasopharyngeal carcinoma radiotherapy, the demethyltransferase FTO promotes the expression of deubiquitylase (OTUB1) expression to counter ferroptosis and bolster the nasopharyngeal carcinoma radioresistance." (PMID 38473842, 2024).